SMIM1 (small integral membrane protein 1 (Vel blood group))
Description:
Regulator of red blood cell formation.
Synonyms: Vel
Tractability: Antibody: UniProt places it where antibodies can reach, with high confidence; its Gene Ontology location is reachable by antibodies, with high confidence; UniProt predicts a signal peptide or a membrane-spanning region.
Gene: Protein-coding gene on chromosome 1 (3,772,655 to 3,776,709, forward strand). Ensembl gene ENSG00000235169.
Subcellular location: Cell membrane
Gene Ontology:
Molecular function: protein binding; protein homodimerization activity
Biological process: nucleate erythrocyte development
Cellular component: cell surface; plasma membrane
Genetic constraint (gnomAD): Loss-of-function variants: 7 observed, 8.05 expected, observed/expected ratio (o/e) 0.87, 90% interval 0.49 to 1.59. That is too few expected variants to judge how well the gene tolerates losing a copy. Missense variants: 95 observed, 105.18 expected, observed/expected ratio (o/e) 0.9, 90% interval 0.76 to 1.07. Synonymous variants: 41 observed, 43.72 expected, observed/expected ratio (o/e) 0.94, 90% interval 0.73 to 1.22.
Homologues: Orthologues: chimpanzee SMIM1 (97% identical), macaque SMIM1 (96% identical), mouse Smim1 (81% identical), rat Smim1 (79% identical), rabbit SMIM1 (78% identical), pig SMIM1 (73% identical), dog SMIM1 (71% identical), guinea pig SMIM1 (69% identical), tropical clawed frog smim1 (65% identical).
Diseases named in the same sentence as SMIM1 in open-access papers:
SMIM1 is named in the same sentence as 13 diseases in open-access papers, as found by Europe PMC text mining. Sharing a sentence is not in itself a finding about the gene and the disease. The quoted sentences say what the papers report.
malaria (2 papers, 2017 to 2019). Malaria is a serious and sometimes fatal disease caused by a parasite that commonly infects a certain type of mosquito which feeds on humans. "Given the possible involvement of SMIM1 in malaria pathogenesis, it is likely that this gene is under selection in the sub-Saharan African population and thus may exhibit distinct genetics different from those currently known." (PMID 30906890, 2019). "A recent study in Kenyan children however did not associate SMIM1 polymorphisms with severe malaria." (PMID 30906890, 2019).
anaemia (1 paper, 2024). "Interestingly, the significant up-regulation of SMIM1, a regulator of red blood cell formation, can be correlated to anaemia, which normally accompanies early CRC diagnosis." (PMID 39766158, 2024).
Anxiety (1 paper, 2013). Intense feelings of nervousness, tension, or panic often arise in response to interpersonal stresses. "We anticipate that this knowledge and the assays herein described to detect deletions in SMIM1 will reduce the burden and anxiety of patients and health care professionals when confronted with the Vel− blood type." (PMID 23505126, 2013).
dyslipidemia (1 paper, 2024). "We found that individuals homozygous for a loss-of-function genetic variant in SMIM1 gene, underlying the blood group Vel, display excess body weight, dyslipidemia, altered leptin to adiponectin ratio, increased liver enzymes, and lower thyroid hormone levels." (PMID 38906141, 2024). "The effect on fat mass, and associated traits, is likely secondary, as suggested by its dependence on BMI, while we foresee a direct effect of SMIM1 on dyslipidemia and liver function as these parameters continue to hold significance even after BMI correction." (PMID 38906141, 2024).
hypothyroidism (1 paper, 2024). Abnormally low levels of thyroid hormone. "Altogether, the observed metabolic phenotype, the increased risk for cardiovascular events, and the expression pattern of SMIM1 are compatible with the fact that its absence results in a state of mild hypothyroidism." (PMID 38906141, 2024).
thyroid dyshormonogenesis (1 paper, 2024). "Lower circulating total thyroid hormones in SMIM1-/- individuals are not due to reduction in thyroid hormone binding globulin and thyroglobulin levels are not elevated, making thyroid dyshormonogenesis an unlikely cause of their altered thyroid status." (PMID 38906141, 2024).
cancer (1 paper, 2024). A tumor composed of atypical neoplastic, often pleomorphic cells that invade other tissues. "Another upregulated L-EV protein in patients with cancer over non-cancer Thy3f nodules is SMIM1, a conserved small protein with a role in red blood cell development." (PMID 39787026, 2024). "With respect to the cancer group, the upregulation of mir-195-3p, KLK11, A1AG2, SMIM1, and the downregulation of mir-3176, mir-205-5p, novel-hsa-mir-208-3p, mir-3529-3p and let-7i-3p, CXCL7, TBB1, ACTN1 and BIP were identified compared with the non-cancer group." (PMID 39787026, 2024).
lipoprotein metabolism disorders (1 paper, 2024). "Interestingly, 20 of the 73 (27%) SMIM1−/− individuals in the Danish cohorts were diagnosed with lipoprotein metabolism disorders versus 13% in the controls (OR = 4.07, FDR = 2.09e−04)." (PMID 38906141, 2024).
SMIM1 also shares sentences with these, for which no sentence is quoted: Disc Degeneration (1 paper); infection (1); Insulin resistance (1); Obesity (1); thyroid cancer (1).